HSPBP1 (HSPA (Hsp70) binding protein 1)
Description:
Inhibits HSPA1A chaperone activity by changing the conformation of the ATP-binding domain of HSPA1A and interfering with ATP binding. Interferes with ubiquitination mediated by STUB1 and inhibits chaperone-assisted degradation of immature CFTR.
Synonyms: FES1
Tractability: Small molecule: a structure with a bound ligand is known; it has a high-quality binding pocket. PROTAC: ubiquitination databases record sites on it; its protein half-life has been measured.
Gene: Protein-coding gene on chromosome 19 (55,262,219 to 55,280,930, reverse strand). Ensembl gene ENSG00000133265.
Subcellular location (Human Protein Atlas): Cytosol; Centrosome; Vesicles
Gene Ontology:
Molecular function: molecular sequestering activity; protein binding; ubiquitin protein ligase binding; adenyl-nucleotide exchange factor activity; enzyme inhibitor activity
Biological process: positive regulation of proteasomal ubiquitin-dependent protein catabolic process; positive regulation of protein ubiquitination; protein folding
Cellular component: extracellular region; endoplasmic reticulum
Genetic constraint (gnomAD): Loss-of-function variants: 31 observed, 35.84 expected, observed/expected ratio (o/e) 0.86, 90% interval 0.65 to 1.17. The upper end of that interval is the gene's LOEUF score, 1.17, which puts it in group 5 of 6, group 1 being the genes least tolerant of losing a copy. Missense variants: 439 observed, 448.53 expected, observed/expected ratio (o/e) 0.98, 90% interval 0.9 to 1.06. Synonymous variants: 199 observed, 192.96 expected, observed/expected ratio (o/e) 1.03, 90% interval 0.92 to 1.16.
Homologues: Orthologues: chimpanzee HSPBP1 (100% identical), macaque HSPBP1 (99% identical), rat Hspbp1 (96% identical), mouse Hspbp1 (95% identical), guinea pig HSPBP1 (95% identical), dog HSPBP1 (94% identical), rabbit HSPBP1 (92% identical), pig HSPBP1 (64% identical), tropical clawed frog hspbp1 (58% identical), zebrafish hspbp1 (51% identical), Drosophila melanogaster CG10973 (15% identical). Paralogues in human: SIL1 (23% identical).
Diseases named in the same sentence as HSPBP1 in open-access papers:
HSPBP1 is named in the same sentence as 18 diseases in open-access papers, as found by Europe PMC text mining. Sharing a sentence is not in itself a finding about the gene and the disease. The quoted sentences say what the papers report.
breast carcinoma (3 papers, 2022 to 2023). "Heat shock protein 70-binding protein 1 (HspBP1), an Hsp70 co-chaperone, is highly expressed in several cancers, including breast cancer, and inversely correlates with tumor aggressiveness." (PMID 37762371, 2023). "A breast cancer risk model consisting of 5 AS events was constructed in our study, which was risk score = (TTC39C|44853|AT*− 2.67) + (HSPBP1|52052|AP*− 4.28) + (MAZ|35942|ES*2.34) + (ANK3|11845|AP*1.18) + (ZC3HAV1|81940|AT*1.59)." (PMID 35988113, 2022). "Here, we show that HspBP1 plays an important role in inhibiting breast cancer tumorigenesis by promoting BRCA1-mediated HR repair." (PMID 35387978, 2022). "In the present study, we found that HspBP1 suppresses breast cancer tumorigenesis and promotes HR-mediated DNA repair, and these effects depend on BRCA1." (PMID 35387978, 2022). "In the present study, we show that HspBP1 has anti-tumorigenic effects in breast cancer in a BRCA1-dependent manner." (PMID 35387978, 2022). "HspBP1 levels are higher in breast cancer tissue compared to normal adjacent tissues, however, it is interesting to note that HspBP1 levels are significantly lower in patients with advanced-stage cancer and with metastasis to auxiliary lymph nodes." (PMID 35387978, 2022). "In summary, we provide evidence that HspBP1 plays an important role in preventing tumorigenesis in BRCA1-proficient breast cancer." (PMID 35387978, 2022). "Moreover, nuclear localization of HspBP1 negatively correlates with increasing breast cancer grades." (PMID 35387978, 2022). "The results show highest levels of nuclear HspBP1 in normal tissues and then progressively lower levels in human breast cancer tissues with increasing cancer grades, suggesting that nuclear HspBP1 expression correlates negatively with advancing clinical stages of breast tumors." (PMID 35387978, 2022). "Since lower expression of HspBP1 in primary breast tissue is correlated to poor patient outcome, HspBP1 may play a protective role in tumorigenesis in breast cancer." (PMID 35387978, 2022). "we looked for a role for HspBP1 in Rad51 foci formation in response to IR in breast cancer cells." (PMID 35387978, 2022). "In the present study, we show that when HspBP1 is either knocked down or overexpressed in BRCA1-proficient breast cancer cells, there were profound changes in tumorigenesis, including anchorage-independent cell growth in vitro and in tumor formation in xenograft models." (PMID 35387978, 2022). "To investigate whether the levels of HspBP1 expression affect tumorigenesis in breast cancer, we stably depleted HspBP1 in BRCA1-proficient (MCF-7 and MDA-MB-231) and BRCA1-deficient (MDA-MB-436) breast cancer cells using HspBP1-specific shRNAs and stably overexpressed GFP-HspBP1 in each cell line." (PMID 35387978, 2022). "Therefore, lower levels of HspBP1 in the nucleus may be a characteristic biological marker for breast cancers that express wild-type BRCA1." (PMID 35387978, 2022). "Thus, we propose that HspBP1 has dual functions in maintaining genomic stability and promoting apoptosis, and HspBP1 expression levels in breast cancer cells could be an important predictor of the likelihood of whether the cancer will respond to radiation." (PMID 35387978, 2022). "It was recently shown that HspBP1 inhibits, in a BRCA1-dependent manner, the tumorigenesis of breast cancer in vitro and in vivo and promotes apoptosis." (PMID 37762371, 2023). "However, HspBP1 did not affect tumorigenic properties in BRCA1-deficient breast cancer cells." (PMID 35387978, 2022). "We then tested the interaction between HspBP1 and BRCA1 in BRCA1 mutant breast cancer cell line HCC1937 and its derivative cell line reconstituted with wild type BRCA1 (HCC1937-BRCA1)." (PMID 35387978, 2022).
breast carcinoma (continued). "Therefore, in breast cancer patients with reduced HspBP1 expression, DNA damage accumulates due to suppressed BRCA1 function, and the ability to remove these damaged cells is decreased as a result of suppressed Hsp70 proapoptotic functions which may synergistically trigger breast cancer progression." (PMID 35387978, 2022). "HspBP1-depleted U2OS cells, HspBP1-depleted breast cancer MCF-7 and MDA-MB-231 cells, and non-malignant MCF10A cells were tested for the ability to form IR-induced Rad51 foci." (PMID 35387978, 2022).
Brain tumor (2 papers, 2018 to 2022). "HspBP1 is localized to the cytoplasm, nucleus, and cell surface of tumor tissue cells, and its expression is upregulated in a number of tumor types, including human hepatocellular, breast, and brain tumors." (PMID 35387978, 2022). "Brain tumor tissue studied by Western blot and immunohistochemistry (IHC) showed a marked increase in the constitutive expression of Hsp27, Hsp90, GRP (glucose regulated proteins) 78 and 75, and Hsc70 (or Hsp70) and the co-chaperone HspBP1 (Hsp70 Binding Protein 1)." (PMID 30189598, 2018).
HIV-1 infection (2 papers, 2023 to 2024). The type species of lentivirus and the etiologic agent of acquired immunodeficiency syndrome (AIDS). "A decrease in HSPBP1 expression due to HIV-1 infection mediated by Tat through its binding to cellular gene promoters is identified." (PMID 39308823, 2024). "HSPs are involved in HIV-1 infection through direct interactions and indirect responses to cellular stress, including HSP40, HSP70, HSPBP1, and HSP90." (PMID 39308823, 2024). "The downregulation of HSPBP1 enhances LTR-driven gene expression, promoting HIV-1 infection (Iyer, Mitra & Mitra, 2022)." (PMID 39308823, 2024). "Finally, through the in vitro cell experiments, we found that the expression level of HSPA14 was inhibited after HIV-1 infection, HSPA14 also inhibited the replication level of the virus and may play a role similar to that of the viral replication inhibitor HspBP1." (PMID 36845091, 2023).
atherosclerosis (1 paper, 2022). A disease characterized by the build-up of fatty material and calcium deposition in the arterial wall resulting in partial or complete occlusion of the arterial lumen. "HSPBP1 (heat shock protein 70-binding protein 1) is a member of the eukaryotic protein family identified as a nucleotide exchange factor for Hsp70 and therefore influences protein quality control, which has already been studied in HIV-1, neuropathology, atherosclerosis and other fields." (PMID 35988113, 2022).
breast tumors (1 paper, 2022). "However, HspBP1 levels inversely correlate to the aggressiveness of breast tumors." (PMID 35387978, 2022).
glioma (1 paper, 2023). A benign or malignant brain and spinal cord tumor that arises from glial cells (astrocytes, oligodendrocytes, ependymal cells). "Phosphatidylethanolamine-binding protein 1 (PEBP1) and Hsp70-binding protein 1 (HSPBP1) were reduced in glioma versus normal brain tissues." (PMID 37762371, 2023).
Huntington disease (1 paper, 2025). Huntington disease (HD) is a rare neurodegenerative disorder of the central nervous system characterized by unwanted choreatic movements, behavioral and psychiatric disturbances and dementia. "Knocking down HspBP1 in neurons rescued neuropathology in a Huntington’s disease mouse model." (PMID 40018685, 2025).
major depressive disorder (1 paper, 2025). An episode of depression lasting two or more weeks without an intervening episode of mania. "Finally, both NR3C1 and HSPBP1 genes were selected because they were differentially expressed in the brains of individuals with mental disorders, with NR3C1 also being differentially expressed in the blood of BHRCS individuals with major depressive disorder." (PMID 40018685, 2025).
multiple sclerosis (1 paper, 2006). A progressive autoimmune disorder affecting the central nervous system resulting in demyelination. "Hspbp1 may facilitate antigen processing by regulating the chaperone function of Hsp70, which has been associated with the presentation of myelin basic protein though MHC class II in multiple sclerosis." (PMID 16670020, 2006).
osteosarcoma (1 paper, 2024). A usually aggressive malignant bone-forming mesenchymal neoplasm, predominantly affecting adolescents and young adults. "Extensive research currently delves into the potential role of individual HSPs such as HSPB1, HSPBP1, and HSP90AA1 in influencing the survival and advancement of osteosarcoma, yet the prognostic value and molecular mechanisms of other HSP family members in osteosarcoma remain to be elucidated 72-77." (PMID 39430254, 2024).
Pasteurella multocida infection (1 paper, 2023). "It was also found that P0910 and ΔOmpH in Pasteurella multocida infection activated the expression of ropE, HSPBP1, FERH, ATP10A, ABCA13, RRP7A, IL-10, IFN-γ, IL-17A, EGFR and dnaJ." (PMID 36977260, 2023).
prostate carcinoma (1 paper, 2025). A carcinoma that arises from epithelial cells of the prostate gland. "First, we employed the downloaded gene matrix to compare the expression of HSPB8, HSPBP1 and HSPA13 levels between normal and prostate cancer samples for validation purposes." (PMID 41190325, 2025). "HSPBP1 expression was significantly higher in prostate cancer groups than in normal controls, while HSPA13 and HSPB8 showed lower expression levels among prostate cancer tissues." (PMID 41190325, 2025). "However, pan-cancer data from GEPIA showed significant differences in terms of HSPB8 expression between normal prostatic tissues and prostate cancer samples while this was not the case for HSPBP1 and HSPA13." (PMID 41190325, 2025).
tumor (8 papers, 2008 to 2024). "In support of this hypothesis, RNAi-mediated depletion of HspBP1 markedly reduced the susceptibility of tumor cells to anticancer drugs." (PMID 19471609, 2008). "This may contribute to the Hsp70-mediated resistance to chemotherapy, as tumor cells with high HspBP1/Hsp70 molar ratios were much more susceptible to anticancer drugs than were those with a low ratio." (PMID 19471609, 2008). "HspBP1 has a tumor-suppressive effect, which is attributed to its role in inhibiting Hsp70 pro-survival activity." (PMID 35387978, 2022). "For instance, it is conceivable that the coordinated interaction between HspBP1 and hsp70 family members regulates tumor cell survival." (PMID 26713263, 2015). "HspBP1 concentrations increase in some forms of cancer, suggesting a possible role in tumor biology." (PMID 26713263, 2015). "Others such as the J domain protein family, HspBP1, TTC4, and FKBPL appear to be associated with more benign tumor phenotypes." (PMID 24278769, 2013). "Conversely, transient ectopic expression of HspBP1 in tumor cells enhanced the cathepsin-mediated cell death induced by anticancer drugs." (PMID 19471609, 2008). "Consequently, HspBP1 plays a role in promoting programmed cell death through cathepsin activation in response to anticancer drugs in tumor cells." (PMID 37762371, 2023). "Since the tumor suppressive effect of HspBP1 is dependent on BRCA1, we predicted that HspBP1 might directly regulate BRCA1 function." (PMID 35387978, 2022). "Evidence has shown that the high expression of HSPBP1 may be related to cytotoxic action and tumor aggressiveness, which can be a protective factor of tumors; this is also consistent with our results." (PMID 35988113, 2022). "Major changes in the expression level of HspBP1 have been found in certain cancer cell lines and indicate that HspBP1 might play a role in tumor biology." (PMID 24454860, 2014). "However, the HspBP1/Hsp70 molar ratio may be lowered considerably in tumor cells (from ~10 to ~2) because the up-regulation of Hsp70 is greater than that of HspBP1 in these cells." (PMID 19471609, 2008). "Similarly, an up-regulation of the HspBP1 NEF was observed in various tumor cell types." (PMID 19471609, 2008). "The 5 genes (TTC39C, HSPBP1, MAZ, ANK3 and ZC3HAV1) where model AS events occurred were analyzed for the differential expression level between normal breast tissue and tumor tissue." (PMID 35988113, 2022). "ST1926 treatment down-regulated a group of oncogenic proteins (SLC2A1, SLC25A6, CBX3, DEK, DDX39B) and up-regulated a group of presumably tumor-suppressing proteins (PEBP1, HspBP1); PADI2 and CMPK1, of unknown function in GBM, were also up-regulated." (PMID 37762371, 2023). "However, when the HspBP1-overexpressing version of each cell line was injected into mice, both BRCA1-proficient cell lines led to markedly lower tumor outgrowth and size than the control, whereas the BRCA1-deficient cells did not." (PMID 35387978, 2022). "However, a sizable number of the co-chaperones, including HspBP1, the JDP family proteins, FKBPL, and TTC4 appear to signal a good prognosis in cancer suggesting that they may have tumor suppressive functions." (PMID 24278769, 2013).
cancer (6 papers, 2013 to 2025). A tumor composed of atypical neoplastic, often pleomorphic cells that invade other tissues. "Aside from cancer, HspBP1 participates in other processes that are relevant to proteostasis and cell signaling." (PMID 26713263, 2015). "In contrast to the BAG proteins, HspBP1 appears to play a suppressive role in a number of types of cancer." (PMID 24278769, 2013).
infection (3 papers, 2011 to 2023). The state of being infected such as from the introduction of a foreign agent such as serum, vaccine, antigenic substance or organism. "CHIP, BAG-1 and HspBP1, respectively, were depleted in mouse BMDCs using specific siRNAs, followed by infection with a recombinant adenovirus that expresses the immune dominant SIINFEKL peptide of ovalbumin fused to luciferase and GFP (Ad-LOG)." (PMID 21283720, 2011). "As controls, expressing Hsc70, SGTA, or HspBP1 when Hsp105 is down-regulated did not significantly restore infection." (PMID 26244546, 2015). "This stimulation requires Hsp105’s nucleotide exchange activity as overexpressing Hsp105 NE*-F or G*-F did not robustly enhance infection (compare third and fourth bars to second bar), and is specific because overexpressing neither Hsc70, SGTA, nor HspBP1 stimulated infection." (PMID 26244546, 2015). "As controls, overexpressing Hsc70, SGTA, or HspBP1 failed to diminish the number of cells harboring the BAP31-positive foci (compare fifth and seventh bar graphs to second), in complete agreement with their inability to stimulate infection when overexpressed." (PMID 26244546, 2015).
neurodegenerative disease (1 paper, 2020). A disorder of the central nervous system characterized by gradual and progressive loss of neural tissue and neurologic function. "The high levels of HspBP1 in neurons may contribute to the development of neurodegenerative diseases, while secreted HspBP1 could modulate the extracellular activities of hsp70s." (PMID 32235396, 2020).
HSPBP1 also shares sentences with these, for which no sentence is quoted: mental disorder (1 paper); ovarian carcinoma (1).